GRIN2B (glutamate ionotropic receptor NMDA type subunit 2B)
Diseases named in the same sentence as GRIN2B in open-access papers (continued):
Sharing a sentence is not in itself a finding about the gene and the disease.
neurodevelopmental disorder (52 papers, 2013 to 2026). A behavioral and cognitive disorder with onset during the developmental period that involves impaired or aberrant development of intellectual, motor, or social functions. "Pathogenic variants in GRIN2B are predominantly associated with neurodevelopmental disorders (NDDs)." (PMID 41146259, 2025). "Pathogenic coding variants and deletions in GRIN2B also cause a spectrum of neurodevelopmental disorders." (PMID 40424442, 2025). "Specifically, mutations V15M and V618G in the GRIN2B gene, which encodes the GluN2B subunit of NMDARs, are implicated in the pathogenesis of GRIN2B-related neurodevelopmental disorders." (PMID 40763259, 2025). "In this work, we have focused on studying the effect of mutations directly linked to GRIN2B neurodevelopmental disorders on NMDAR–BK associations." (PMID 40763259, 2025). "Such variants were identified in GRIN2A and GRIN2B genes in individuals diagnosed with neurodevelopmental disorders." (PMID 38214768, 2024). "Three patients harbored four predicted PL/P variants in other genes causing neurodevelopmental disorders (GRIN2B, MADD, TRPM3 and ZEB2), leading to alternative diagnoses for them." (PMID 38566815, 2024). "Autosomal dominant intellectual development disorder-6 (MRD6) is a neurodevelopmental disorder caused by a genetic mutation in the grin2b gene." (PMID 37927744, 2023). "The GRIN2B-related neurodevelopmental disorder is a rare disease caused by mutations in the GRIN2B gene, which encodes the GluN2B subunit of NMDA receptors." (PMID 36704660, 2022). "GRIN2B-related neurodevelopmental disorder is a rare disease caused by mutations in the GRIN2B gene." (PMID 36704660, 2022). "Together, the existing data provide insight into the pathophysiological mechanisms that underlie GRIN2B-related neurodevelopmental disorder and emphasize the importance of comparing the effects of individual, disease-associated variants." (PMID 36704660, 2022). "Together, the existing data are beginning to provide insight into the pathophysiological mechanisms that underlie GRIN2B-related neurodevelopmental disorder and link specific variants to the development of clinical symptoms." (PMID 36704660, 2022). "In a large cohort of individuals diagnosed with neurodevelopmental disorders, the prevalence of de novo GRIN2B variants that are likely pathogenic was 0.2%." (PMID 36704660, 2022). "Additional sequencing of GRIN2B in individuals with ID and other neurodevelopmental disorders has identified a large number of disease-associated GRIN2B variants." (PMID 36704660, 2022). "For example, it has been suggested that GRIN2A mutations predominantly lead to an epileptic phenotype while GRIN2B variants are more likely to lead to neurodevelopmental disorders." (PMID 34776984, 2021). "They showed that GRIN2A variants are commonly associated with an epileptic phenotype but that GRIN2B variants are commonly found in patients with neurodevelopmental disorders." (PMID 34685369, 2021). "Mutations in GRIN2A and GRIN2B encoding the alpha and beta-2subunits (NR2A and NR2B) of the glutamate-activated N-methyl-D-aspartate (NMDA) receptor areassociated with several neurodevelopmental disorders." (PMID 24272827, 2014). "For instance, the gene GRIN2B encodes a member of the ionotropic glutamate receptor superfamily and plays a major role in brain development and synaptic plasticity, with mutations in this gene often associated with neurodevelopmental disorders." (PMID 41219721, 2025). "The majority of individuals with GRIN2B‐associated neurodevelopmental disorders exhibit intellectual disability, developmental delay, schizophrenia, epilepsy, autism spectrum disorder, microcephaly, cortical visual impairment, and malformations of cortical development in the clinic." (PMID 40568341, 2025).
neurodevelopmental disorder (continued). "These mutations are linked to GRIN2B neurodevelopmental disorders and reported in the literature." (PMID 40763259, 2025). "A similar clinical study was performed on 2 female patients, one 18 months old and the other 4 years old to investigate the effects of L-serine supplementation (500 mg/kg/day in 4 doses) in GRIN2B-related neurodevelopmental disorder that arises out of a loss of function of GRIN2B gene." (PMID 37626614, 2023). "The exact prevalence of neurodevelopmental disorders caused by the grin2b gene is currently unknown, and the cases reported in medical literature to date are very rare." (PMID 37927744, 2023). "All reported cases of neurodevelopmental disorders associated with the grin2b gene that were confirmed through molecular genetic testing in parents have been found to be caused by a new (de novo) pathogenic variant or deletion in the grin2b gene." (PMID 37927744, 2023). "Human NMDAR genes are highly intolerant to variations, and mutations in Grin2a and Grin2b, the genes encoding the GluN2A and GluN2B subunits, respectively, are a major cause of neurodevelopmental disorders associated with childhood epilepsy and cognitive impairments." (PMID 34354080, 2021). "Additionally, the reasons behind why both excessive and insufficient receptor activity leads to similar neurological issues in individuals with neurodevelopmental disorders linked to the grin2b gene remain unclear." (PMID 37927744, 2023). "Given the reports of the importance of GRIN2B in cell differentiation, we reasoned that mutations in GRIN2B in human may lead to a neurodevelopmental disorder not only through its well-known role in synaptic plasticity but through a role in differentiating neural stem cells." (PMID 29937144, 2018). "Although perampanel and memantine both target glutamate receptors, their efficacy on GRIN2B-related neurodevelopmental disorders varies." (PMID 41146259, 2025). "It has been revealed that the abnormal function of the GRIN2B protein is related to the onset and progression of neurodevelopmental disorders." (PMID 40568341, 2025). "Mutations in the GRIN2B gene, encoding the GluN2B subunit of NMDA receptors, are linked to neurodevelopmental disorders." (PMID 40763259, 2025). "We utilized a novel model of GRIN2B‐related neurodevelopmental disorder in which the Grin2b gene was knocked out of Long–Evans rats." (PMID 40827489, 2025). "We identified 48 variants in the M3 transmembrane helix across GRIN1, GRIN2A, and GRIN2B in 56 patients with neurological and/or neurodevelopmental disorders." (PMID 38538865, 2024). "The prevalence of GRIN2B-related neurodevelopmental disorders among individuals with neurodevelopmental disorders and/or childhood-onset epilepsy is around 0.2%." (PMID 37927744, 2023). "This is especially valuable in cases where there is substantial heterogeneity and variability within the study population, such as in GRIN2B-related neurodevelopmental disorder (GRIN2B-NDD)." (PMID 38144875, 2023). "Our objective is to further evaluate the effectiveness of L-serine for GRIN2B-related neurodevelopmental disorder (GRIN2B-NDD), using an n-of-1 trial design, increasing the level of evidence." (PMID 38144875, 2023). "A final important issue is the use of Grin2b knockout animals to understand GRIN2B-related neurodevelopmental disorder pathophysiology." (PMID 36704660, 2022). "GRIN2B-related neurodevelopmental disorder is typically discovered in pediatric patients, with the onset of symptoms often occurring during the first few years of age." (PMID 36704660, 2022).
neurodevelopmental disorder (continued). "Disease-associated missense mutations in GRIN2B are more likely to result in neurodevelopmental disorders, such as ASD, as compared to other subunits, highlighting the significant developmental requirements for GluN2B." (PMID 36138431, 2022). "In an analysis of pathophysiological mechanisms of GRIN2B-related neurodevelopmental disorder, it is important to consider the variability in clinical phenotypes that are observed in individuals with the disease." (PMID 36704660, 2022). "Researchers are uncertain how improper NMDA receptor activation compromises typical brain growth and development or why excessive or inadequate activity manifests in neurological complications in people with GRIN2B-related neurodevelopmental disorders." (PMID 35893069, 2022). "The development of whole-genome sequencing technologies has allowed for major sequencing efforts of patients with neurodevelopmental disorders, and has underscored the importance of GRIN2B in human brain development." (PMID 29937144, 2018). "Together, these findings suggest that Grin2b may act as a critical molecule linking synaptic neurotransmission and neurodevelopmental disorders." (PMID 41150532, 2025). "Moreover, it summarizes the phenotypic and genotypic features of an additional 98 cases of GRIN2B-related neurodevelopmental disorders from the literature." (PMID 41146259, 2025). "Together, these findings suggest that Grin2b may serve as a critical molecule linking synaptic neurotransmission and neurodevelopmental disorders." (PMID 41150532, 2025). "To date, a few 100 individuals with GRIN2B-related neurodevelopmental disorder are published." (PMID 40687877, 2025). "Together, these findings suggest Grin2b may serve as a critical molecule linking synaptic neurotransmission and neurodevelopmental disorders." (PMID 41150532, 2025). "Notably, this is the second study to report on the efficacy of memantine in GRIN2B-related neurodevelopmental disorders." (PMID 41146259, 2025). "The penetrance of GRIN2B-related neurodevelopmental disorders is thought to be 100%." (PMID 37927744, 2023). "This information could help guide the development and application of effective therapeutic strategies for treating individuals with GRIN2B-related neurodevelopmental disorder." (PMID 36704660, 2022). "Given the complexity of NMDAR expression patterns, subcellular trafficking, and function, understanding the pathophysiology of GRIN2B-related neurodevelopmental disorder requires systematic investigation into the molecular and cellular phenotypes generated by disease-associated variants." (PMID 36704660, 2022). "GRIN2B-related neurodevelopmental disorder affects both males and females." (PMID 36704660, 2022). "Mutations identified in GRIN2B-related neurodevelopmental disorder patients are de novo variants that are not found in siblings, parents, or other healthy individuals." (PMID 36704660, 2022). "Additionally, variation in GRIN2A (the gene for the NR2A subunit) is commonly associated with an epileptic phenotype, while that in GRIN2B (the gene for the NR2B subunit) is commonly found in patients with neurodevelopmental disorders." (PMID 32093213, 2020). "Given this information and the observation that around 14% of patients with GRIN2B-related neurodevelopmental disorders display cortical malformations in MRI, it was hypothesized that pathogenic variants in GluN2B might act by interfering with neuronal differentiation." (PMID 36704660, 2022). "Thus, dysregulation of NMDAR expression, trafficking, and function by such pathways may be integral to the pathophysiological mechanisms of GRIN2B-related neurodevelopmental disorder." (PMID 36704660, 2022). "Indeed, no formal diagnostic criteria for GRIN2B-related neurodevelopmental disorder have been established (Platzer and Lemke, 1993; revised 2021)." (PMID 34212862, 2021).
neurodevelopmental disorder (continued). "We demonstrate that removing the target exon significantly increased protein translation (between 1.4-5.5 fold) in a luciferase reporter assay for four of six prioritised target 5’UTR exons in neurodevelopmental disorder genes (CTCF,GRIN2B,KRIT1, andTSC1)." (PMID 41573882, 2025). "GRIN2B-related disorders seem to have the highest prevalence among all GRIN-related disorders with 5.91 predicted incidence per 100,000 births; This was previously reported to make up ~0.22% of the total neurodevelopmental disorders." (PMID 37414777, 2023).
neurological disorders (37 papers, 2013 to 2025). "The autosomal dominant intellectual developmental disorder associated with the grin2b gene (MRD6) is a rare neurological disorder, and less than 100 cases have been reported so far." (PMID 37927744, 2023). "The recent discovery of de novo CNV deletions of Axin1 and exome variants of the Grin2C family member Grin2B associated with ASDs further exemplify the utility of the synapse analysis pipeline in the functional analysis of risk genes of neurological disorders." (PMID 24633176, 2014). "We next compared our genes to gene sets of ASD or other neurological disorders and found that CHD8, DYRK1A, GRIN2B, MBD5 and SCN2A overlapped with the ASD gene sets (FDR ≤ 0.1) reported in previous large-scale ASD studies." (PMID 32193494, 2020).
tumor (29 papers, 2011 to 2025). "Together with TMEM140, TEAD2, OR1J2, and GRIN2B, many other genes were commonly mutated across the tumor samples, however the recurrence always occurred when examining multiple metastatic samples of the same individual (T07–11 or T04–05 corresponding respectively to patients P06 and P04)." (PMID 29510530, 2018). "We identified 3 driver genes (FCGBP, GRIN2B, and FRY), and recurrent truncating mutations in FRY impaired its tumor-suppressive function and promoted tumor proliferation." (PMID 35993362, 2022). "The calcium signaling pathway (hsa04020) contained 23 genes (p = 8.81 × 10−7), including key receptors such as SLC8A2, HTR2C, GRIN1, CACNA1I, and GRIN2B, which regulate intracellular calcium levels and tumor microenvironment dynamics via glutamate interactions." (PMID 40406701, 2025). "Based on the known annotation of marker genes from the literature, we grouped cells of nine clusters into four cell types: GNP-like tumor cells (expressing Math1 and Grin2b), microglia (expressing Aif1 and Cd68), T cells (expressing Cd3d and Cd3e), and endothelial cells (expressing Cldn5 and Cdh5)." (PMID 34210306, 2021). "Five molecules (DAPK1, TIMP3, GRIN2B, SLC5A8, and CDH1) are tumor suppressor genes consistently downregulated and/or hypermethylated in GC and in H. pylori infected children." (PMID 32117120, 2020). "In the context of our findings, mir-148a under-expression in tumor and stroma potentially leads to increased expression of its target genes such as BCL2, GRIN2B, and SELL, which play roles including adaptive immune system regulation." (PMID 31150430, 2019). "We did not detected overexpression of GRIN2B in tumor tissues in our bioinformatic analysis." (PMID 37553583, 2023).
cancer (25 papers, 2010 to 2024). A tumor composed of atypical neoplastic, often pleomorphic cells that invade other tissues. "In addition, GRIN2B was mutated in two different samples but this event seems irrelevant in cancer biological processes." (PMID 29510530, 2018). "By querying the TCGA through cBioPortal, it was found that the GRIN2B gene is altered in 5% of all cancers, with melanoma prevalence." (PMID 36768862, 2023). "The comparison of data between cancer samples and their normal tissue counterparts revealed that, among the GRIN gene family, GRIN2B exhibits the highest level in the majority of TCGA cancer subtypes." (PMID 36139568, 2022). "GRIN2B (Glutamate Ionotropic Receptor NMDA Type Subunit 2B) codifies for a glutamate receptor expressed on the surface of cancer cells, and its hypermethylation and silencing have been reported in several solid tumors, including GC." (PMID 32117120, 2020). "In silico analysis, by querying the TCGA database and comparing the cancer expression levels with their normal tissue counterparts, demonstrates that, among the GRIN gene family, GRIN2B exhibits the highest expression in the majority of cancer subtypes." (PMID 36768862, 2023). "Unlike GRIN2A, GRIN2B was not annotated as a cancer driver gene, according to cBioPortal algorithms." (PMID 36768862, 2023).
psychiatric disorder (21 papers, 2013 to 2026). A disorder characterized by behavioral and/or psychological abnormalities, often accompanied by physical symptoms. "In addition, variants in the NMDAR 2B subunit gene (GRIN2B) have been linked to schizophrenia, mental illnesses, and brain plasticity." (PMID 35186144, 2022). "Moreover, to comprehensively assess impact of rare variants affecting NMDA signaling in case of psychiatric disorders, genes beyond GRIN2B should be evaluated in the future studies." (PMID 27616045, 2016). "Focusing on miR-223, we then examined the expression of proven miR-223 targets, GRIA2 and GRIN2B, which are of relevance to psychiatric disorders, in our cohort using qRT-PCR with normalization to the unaltered and reliable for postmortem studies 18S rRNA." (PMID 31775160, 2020). "Given the importance of the Glun2B subunit of NMDA receptor for maturation and plasticity of the central nervous system, it is not surprising that over 60 variants of GRIN2B have been associated with heterogeneous neurodevelopmental and psychiatric disorders." (PMID 34440367, 2021). "In fact, GRIN2B variants have been associated not only with ADHD, but also with cognitive deficits in heterogeneous neurodevelopmental and psychiatric disorders, including autism spectrum disorders, Alzheimer’s and Parkinson’s diseases, bipolar disorder, and schizophrenia." (PMID 34440367, 2021).
brain disorder (10 papers, 2015 to 2024). A disease affecting the brain or part of the brain. "However, it remains unclear whether GluN2B dysfunction leads to abnormal neural connectivity and whether such impairments could be associated with the pathophysiology of GRIN2B-related brain disorders." (PMID 38704508, 2024). "In line with the strong involvement of GRIN2B in diverse brain disorders, mice carrying a conventional homozygous deletion of Grin2b display impaired suckling, neonatal death during postnatal day (P) 1–3, and impaired hippocampal long-term depression (LTD) in neonates." (PMID 32353004, 2020).
movement disorder (6 papers, 2012 to 2025). Neurological conditions resulting in abnormal voluntary or involuntary movement, which may impact the speed, fluency, quality and ease of movement. "In a population with chronic mental illness, various tag SNPs in 7 candidate genes (GRIN2B, GRIN2A, HSPG2, DRD3, DRD4, HTR2C, and NQO1) reached nominally significant (p≤0.05) associations with drug-induced movement disorders." (PMID 23226551, 2012).
GRIN2B also shares sentences with these, for which no sentence is quoted: Stroke (35 papers); ischemia (26); memory impairment (24); Cerebral ischemia (22); ischemic stroke (20); neurodegenerative disease (17); bone cancer (11); encephalitis (11); migraine (10); peripheral nerve injury (9); status epilepticus (9); neuropathy (8); Tinnitus (8); brain injury (7); cognitive disorder (7); injury (7); cerebral infarction (5); neuroblastoma (5); pancreatic cancer (5); Seizure (5); brain tumor (4); cortical dysplasia (4); focal epilepsy (4); Hyperammonemia (4); infection (4); mental disorder (4); neuropathic pain (4); Obesity (4); Parkinson’s (4); post-traumatic stress disorder (4).
A further 145 diseases each share a sentence with GRIN2B in 4 papers or fewer.